SOX4 (SRY-box transcription factor 4)
Diseases named in the same sentence as SOX4 in open-access papers (continued):
Sharing a sentence is not in itself a finding about the gene and the disease.
cancer (continued). "However, in cancer cell lines DLD1, HCT116, and H1975, siβ-catenin did not affect SOX4 expression, indicating that SOX4 expression does not universally require Wnt signaling." (PMID 29977599, 2018). "Interestingly, Metformin had no inhibiting effect on SOX4 and AXIN2 levels in non-cancer cell lines (HEK293T, MRC5, and C2C12)." (PMID 29977599, 2018). "Confirming the idea of a positive correlation, RNA-sequencing data from the Cancer Cell line Encyclopedia (CCLE) showed that B-ALL and AML cell lines showed a strong positive correlation between the expression of CASC15 and SOX4, while DLBCL and non-hematopoietic tumor cell lines did not." (PMID 28724437, 2017).
infection (8 papers, 2014 to 2025). The state of being infected such as from the introduction of a foreign agent such as serum, vaccine, antigenic substance or organism. "Toward this end, we transduced congenic distinct P14 CD8+ T cells with vector or shRNA targeting Sox4 and transferred them into mice at a 50/50 ratio, followed by infection of the recipients with LCMV-Arm+." (PMID 39804040, 2025). "By contrast, primary infection of goats was identified with a rise of SOX4/IL-17A and γδ T cell receptor transcripts, highlighting a different role for γδ T cell subpopulations during vaccination and infection." (PMID 36788233, 2023). "In this study, we initially showed that Sox4 expression is induced during the infections of enterovirus 71 (EV71), influenza A virus (IAV), hepatitis C virus (HCV), and vesicular stomatitis virus (VSV)." (PMID 33517839, 2021). "Sox4 was found to suppress the host innate immunity to facilitate pathogen infection." (PMID 36671463, 2022). "Here, we determined the roles of Sox4 in the regulation of host immunity and pathogen infection." (PMID 33517839, 2021). "Therefore, Sox4 is activated during the infections of VSV, HCV, IAV, and EV71." (PMID 33517839, 2021). "To investigate the role of Sox4 in MPEC-to-memory T-cell transition, we sorted vector- or shSox4-transduced MPECs in D8 cells and then cotransferred them into infection-matched mice." (PMID 39804040, 2025). "Here, we demonstrated that the sex-determining region Y-box 4 (Sox4) acts as a master regulator to hijack TLR networks at multiple stages and facilitate pathogen infection by a unique mechanism." (PMID 33517839, 2021). "We demonstrated that Sox4 represses all TLRs except TLR2, implicating that Sox4 may play general roles in regulating the infections of vast number of pathogens, including viruses, bacteria, fungi, and protozoan, although further studies are needed." (PMID 33517839, 2021). "Interestingly, the tuft cell neuronal regeneration-related protein (Nrep) and Sox4 were increasingly upregulated over time in non-permissive mice, potentially contributing to protection against infection." (PMID 36883013, 2023). "Indeed we find a reduction of crypt-base located Sox4 levels after infection and this repression did not occur in DMH1-treated animals." (PMID 35559665, 2022).
adenocarcinoma (4 papers, 2009 to 2020). A common cancer characterized by the presence of malignant glandular cells. "In a study of NSCLC, expression of this lncRNA in the adenocarcinoma subtype was associated with inhibition of EMT through regulation of SOX4." (PMID 29701689, 2018). "We analyzed the reciprocal expression regulation of miR-31 and SOX4 in esophageal squamous and adenocarcinoma cell lines by qRT-PCR and Western blotting using overexpression and shRNA knock-down approaches." (PMID 25644061, 2015). "We also found that SOX4, ORC6, and CCDC34 were more highly expressed in adenocarcinoma tissue than in normal gastric tissue using Western blot (WB) assays and immunohistochemistry (IHC)." (PMID 33188157, 2020). "Moreover, SOX4, ORC6, and CCDC34 are located mainly in the nucleus of adenocarcinoma tissues." (PMID 33188157, 2020).
haematological disease (2 papers, 2018 to 2023). "B/My MPAL blasts depicted significant overexpression genes such as STMN1 and SOX4, which have been previously associated with other hematological malignancies, such as AML and ALL." (PMID 37845689, 2023).
neurodegenerative disease (2 papers, 2019 to 2022). A disorder of the central nervous system characterized by gradual and progressive loss of neural tissue and neurologic function. "Interestingly, several genes involved in neurodegenerative diseases, such as PATZ1, SOX-4." (PMID 35746678, 2022).
neurodevelopmental disorder (2 papers, 2024). A behavioral and cognitive disorder with onset during the developmental period that involves impaired or aberrant development of intellectual, motor, or social functions. "In contrast, both SOX4 and SOX11 genes within the same C group (SoxC) of the Sox gene family have been associated with neurodevelopmental disorders." (PMID 39057025, 2024).
CNS tumours (1 paper, 2012). "To assess the gene expression profile of hypoxia-induced genes in brain and CNS tumours, we queried the oncomine database for the following genes; HIF1A1, VEGFA, MMP2, NEDD9, SOX4, and SOX9." (PMID 22570651, 2012).
peripheral neuropathy (1 paper, 2022). A disorder affecting the peripheral nervous system. "Sox4 marks SCs in peripheral neuropathy and is normally expressed in immature and promyelinating SCs." (PMID 36134665, 2022).
retinopathy (1 paper, 2022). "The diabetic mice model was induced by STZ, and the expression of SOX4 increased, while it was aggravated in STZ-induced mice with retinopathy." (PMID 35573654, 2022).
SOX4 also shares sentences with these, for which no sentence is quoted: adenoid cystic carcinoma (7 papers); clear cell renal cell carcinoma (2); diabetic nephropathy (2); dysplastic nevi (2); esophageal adenocarcinoma (2); Glucose intolerance (2); idiopathic pulmonary fibrosis (2); laryngeal squamous cell carcinoma (2); liver (2); Neurodevelopmental delay (2); pancreatic adenocarcinoma (2); renal fibrosis (2); adenoid cystic carcinoma of salivary gland (1); adenovirus infection (1); age (1); astrocytic tumor (1); basal cell carcinoma (1); benign prostatic hyperplasia (1); bipolar disorder (1); brain cancer (1); brain tumor (1); breast disease (1); campomelic dysplasia (1); central neurocytoma (1); Coffin–Siris syndrome 9 (1); colitis (1); congenital heart disease (1); cutaneous melanoma (1); ductal carcinoma in situ (1); ductal carcinomas (1).
A further 42 diseases each share a sentence with SOX4 in 1 paper.